MRPL11 (mitochondrial ribosomal protein L11)
Synonyms: L11mt; MRP-L11; CGI-113; uL11m
Tractability: Small molecule: a structure with a bound ligand is known. PROTAC: ubiquitination databases record sites on it; its protein half-life has been measured.
Target class: Other cytosolic protein
Gene: Protein-coding gene on chromosome 11 (66,435,075 to 66,466,738, reverse strand). Ensembl gene ENSG00000174547.
Subcellular location: Mitochondrion
Subcellular location (Human Protein Atlas): Mitochondria; Primary cilium
Pathways (Reactome):
Metabolism of proteins: Mitochondrial ribosome-associated quality control; Mitochondrial translation elongation; Mitochondrial translation initiation; Mitochondrial translation termination
Gene Ontology:
Molecular function: protein binding; RNA binding; large ribosomal subunit rRNA binding; structural constituent of ribosome
Biological process: mitochondrial translation; translation
Cellular component: mitochondrial large ribosomal subunit; mitochondrion; mitochondrial inner membrane; mitochondrial ribosome; ribosome
Genetic constraint (gnomAD): Loss-of-function variants: 17 observed, 16.57 expected, observed/expected ratio (o/e) 1.03, 90% interval 0.7 to 1.53. The upper end of that interval is the gene's LOEUF score, 1.53, which puts it in group 6 of 6, group 1 being the genes least tolerant of losing a copy. Missense variants: 241 observed, 232.3 expected, observed/expected ratio (o/e) 1.04, 90% interval 0.93 to 1.15. Synonymous variants: 107 observed, 95.92 expected, observed/expected ratio (o/e) 1.12, 90% interval 0.95 to 1.31.
Homologues: Orthologues: chimpanzee MRPL11 (100% identical), macaque MRPL11 (97% identical), dog MRPL11 (93% identical), guinea pig MRPL11 (93% identical), pig MRPL11 (91% identical), rabbit MRPL11 (89% identical), mouse Mrpl11 (88% identical), rat mrpl11 (88% identical), tropical clawed frog mrpl11 (66% identical), zebrafish mrpl11 (65% identical), Caenorhabditis elegans mrpl-11 (41% identical), Drosophila melanogaster mRpL11 (38% identical). Paralogues in human: RPL12 (19% identical).
Diseases named in the same sentence as MRPL11 in open-access papers:
MRPL11 is named in the same sentence as 14 diseases in open-access papers, as found by Europe PMC text mining. Sharing a sentence is not in itself a finding about the gene and the disease. The quoted sentences say what the papers report.
head and neck squamous cell carcinoma (2 papers, 2020 to 2021). A squamous cell carcinoma that arises from any of the following anatomic sites: lip and oral cavity, nasal cavity, paranasal sinuses, pharynx, larynx, and salivary glands. "In contrast, decreased MRPL11 is considered a potential biomarker of primary head and neck squamous cell carcinoma." (PMID 34772924, 2021).
lung carcinoma (2 papers, 2020 to 2025). "Of these, Aco2, Idh2, Ndufs1, Hadh, Dlat, Itgam, Dlat, Hadha, Mrpl11, Dlst, and Hspd1 show potential as oncoproteins and tumor suppressors and warrant further study for their possible role in inflammation-driven lung cancer." (PMID 40429836, 2025).
neuroblastoma (2 papers, 2020 to 2022). Neuroblastoma (NB) is the most common solid, extracranial childhood tumor. "MRPL11 is highly expressed in stage 4 neuroblastoma and is associated with a poor prognosis." (PMID 35719986, 2022). "We found several highly significant RBPs including RPL22L1, RNASEH2A, PTRH2, MRPL11 and AFF2, which remain uncharacterised in neuroblastoma." (PMID 32707690, 2020).
cholangiocarcinoma (1 paper, 2022). A carcinoma that arises from the intrahepatic biliary tree (intrahepatic cholangiocarcinoma) or from the junction, or adjacent to the junction, of the right and left hepatic ducts (hilar cholangiocarcinoma). "To determine the role of 4-key-genes in cholangiocarcinoma CSCs, we first knocked down SDHAF2, MRPS34, MRPL11 and COX8A in HCCC9810 cell and overexpressed them in RBE cell, respectively." (PMID 35841118, 2022). "In our study, we demonstrated that CSCs in cholangiocarcinoma have different methionine metabolic features, and 4-key-genes (SDHAF2, MRPS34, MRPL11 and COX8A) could promote ICC stemness in a MAT2A-dependent manner." (PMID 35841118, 2022).
colon cancer (1 paper, 2021). "Moreover, GTPase ERAL1 and mitochondrial ribosomal proteins MRPL11, 15, 30, 37, 40, and 52 have great potential to serve as potential therapeutic targets for colon cancer treatment." (PMID 33806918, 2021). "Finally, GTPase ERAL1 and mitochondrial ribosomal proteins including MRPL11, 15, 30, 37, 40, and 52 were identified as hub proteins of berberine-treated colon cancer cells." (PMID 33806918, 2021). "In addition, we found that berberine could impair mitochondrial function by inhibiting mitochondrial protein, and GTPase ERAL1 as well as mitochondrial ribosomal proteins including MRPL11, 15, 30, 37, 40, and 52 have potential to serve as candidate targets of berberine in colon cancer cells." (PMID 33806918, 2021). "Finally, the GTPase ERAL1, mitochondrial ribosomal proteins ERAL1, MRPL11, MRPL15, MRPL30, MRPL37, MRPL40, and MRPL52 were determined to be hub proteins with a commonly down-regulated trend in four berberine-treated colon cancer cell lines." (PMID 33806918, 2021).
lymph node metastasis (1 paper, 2022). "In addition, multivariate analysis showed that SDHAF2, MRPL11, COX8A, serum carbohydrate antigen 19-9 (CA19-9), tumor size and lymph node metastasis are independent factors for overall survival (OS) of ICC patients with adjuvant TACE." (PMID 35841118, 2022). "Since multivariate analysis suggested that CA19-9, tumor size, lymph node metastasis, SDHAF2, MRPL11 and COX8A are independent factors for OS of ICC patients with adjuvant TACE, a nomogram that included all these risk factors was constructed (C-index: 0.85, 0.81–0.89)." (PMID 35841118, 2022).
squamous cell carcinoma (1 paper, 2019). A carcinoma arising from squamous epithelial cells. "Moreover, in samples from clinical squamous cell cancer, six genes (GAL, GSTP1, MRPL11, MRPL21, SF3B2, and YIF1A) at 11q13.1–13.3 and one gene (GALR1) at 18q23 showed significant differences in expression between normal and tumor samples." (PMID 31552180, 2019).
tumor (5 papers, 2006 to 2024). "Other MRPs such as MrpL11, MrpL12 and MrpL28 have been reported to be differentially expressed in tumour cells or tissue." (PMID 28056857, 2017). "One group was associated with rapid proliferation, oxidative phosphorylation, invasiveness, and tumor size (MRPS23, MRPL11, CKS2, LSM3, TBX3, MSN) and another with hypoxia tolerance, anaerobic metabolism, and high lactate content (PDK2, KLF3)." (PMID 17054779, 2006). "Multivariate analysis identified MRPL11, TBX3, and PDK2 expression as independent prognostic gene variables, whereas only tumor volume was identified in a model containing the clinical variables." (PMID 17054779, 2006). "Additionally, studies suggest that high expressions of CYFRA 21-1 and IL-6 in tumor tissue, IL-17 surrounding tumor cells, and the genes SDHAF2, MRPS34, MRPL11, and COX8A in cancer stem cells are associated with a poor prognosis, thus offering novel prognostic avenues for exploration." (PMID 39170710, 2024).
cancer (2 papers, 2021 to 2024). A tumor composed of atypical neoplastic, often pleomorphic cells that invade other tissues. "SGCE’s role in cell structure and signalling suggests its involvement in cancer progression, while MRPL11’s involvement in mitochondrial metabolism points to its potential role in cancer biology." (PMID 39272878, 2024). "Then, choosing MRPL11 (UL11m) that was previously evaluated in cancer cells and MRPS22 (mS22) as representatives of the large and small mitoribosome subunits, we observed that the DHX30-depleted cells showed reduced expression of these two genes at both the RNA and protein levels." (PMID 34503222, 2021).
MRPL11 also shares sentences with these, for which no sentence is quoted: cervical cancer (1 paper); COVID-19 (1); esophageal squamous cell carcinoma (1); hepatoma (1); preeclampsia (1).